SNORD108 (small nucleolar RNA, C/D box 108)
Synonyms: HBII-437
Gene: Small nucleolar RNA gene on chromosome 15 (24,986,925 to 24,986,995, forward strand). Ensembl gene ENSG00000239014.
Gene Ontology:
Biological process: RNA processing
Cellular component: nucleolus
Homologues: Orthologues: chimpanzee SNORD108 (100% identical), macaque SNORD108 (94% identical), dog SNORD108 (70% identical).